SNORD39 (Small nucleolar RNA SNORD55/SNORD39 )
Synonyms: LOC124900521
Gene: Small nucleolar RNA gene on chromosome 2 (237,869,904 to 237,869,982, forward strand). Ensembl gene ENSG00000263723.
Gene Ontology:
Biological process: RNA processing
Cellular component: nucleolus
Homologues: Orthologues: chimpanzee SNORD39 (96% identical), macaque SNORD39 (81% identical), guinea pig SNORD39 (53% identical), tropical clawed frog SNORD39 (53% identical), guinea pig SNORD39 (52% identical), tropical clawed frog SNORD39 (51% identical). Paralogues in human: SNORD55 (73% identical), SNORD39 (58% identical), SNORD39 (52% identical).